MTAP (methylthioadenosine phosphorylase)
Diseases named in the same sentence as MTAP in open-access papers (continued):
Sharing a sentence is not in itself a finding about the gene and the disease.
glioma (continued). "First, we determined the inhibitory effect of MRTX1719 on the growth and proliferation of MTAP‐deficient glioma cells (Hs683 and U‐118MG), MTAP‐normal glioma cells (GL261), MTAP‐normal microglial (HMC3), and neuronal cells (SH‐SY5Y)." (PMID 39711357, 2024). "It is in our data that the proportion of MTAP expression less than 20% is very high, accounting for about 32.9%, which shows that MTAP deletion is common in glioma." (PMID 39711357, 2024). "MTAP deficiency leads to increased expression of PROM1/CD133 which results in enhanced tumorigenicity of GBM cells and also promotes glioma stem-like cell (GSC) formation." (PMID 36572880, 2022). "We also investigated the effects of culture medium on SDMA levels of MTAP-deleted and WT glioma cells." (PMID 34244484, 2021). "In this study, we found that highly elevated MTA levels found in MTAP-deleted glioma cell lines in culture cannot be extrapolated to primary GBMs." (PMID 34244484, 2021). "MTAP expression was evaluated in 507 glioma patients by immunohistochemistry (IHC), and the expression levels were associated with patients’ clinicopathological features." (PMID 32093414, 2020). "In glioma cell lines, MTAP was edited, and following MTAP overexpression and knockout (KO), a transcriptome analysis was performed by NanoString Pan-Cancer Pathways panel." (PMID 32093414, 2020). "Next, in a set of eleven established and seven short-term primary gliomas cells, we compared MTAP copy number with MTAP mRNA and protein expression by RT-qPCR and Western blot, respectively." (PMID 32093414, 2020). "Clearly, a better understanding of the molecular changes of MTAP-depleted cells is needed to exploit this direct and indirect molecular vulnerability, increasing the efficacy of treatment in patients with glioma." (PMID 32093414, 2020). "Of note, 40% (6/15) of high-grade glioma (HGG; WHO grade III–IV) cell lines presented loss of MTAP expression, contrasting with 0% in low-grade glioma (LGG; WHO grade I–II) cell lines (0/3)." (PMID 32093414, 2020). "In LGG, the ceRNAs shared by MTAP and CDKN2A contained many genes highly associated with gliomas and other cancers, such as IDH1 and CDK4/6." (PMID 31719831, 2019). "High frequency of MTAP deletion has been described in high-grade gliomas, namely in GBMs, in agreement with the present study, and also our recent report of MTAP protein expression in more than 85% of pilocytic astrocytomas." (PMID 27172220, 2016). "Prior to our report, a similar MTAP-ANRIL fusion gene was reported in a glioma tumor resulting from fusion of MTAP exon 4 with exon 2 of ANRIL and the resultant transcript contained 27 amino acids from the non-coding gene." (PMID 26909863, 2016). "MTAP‐deficient gliomas were surrounded by a large number of MTAP‐expressing normal cells, and the presence of these cells significantly reduced the inhibitory effect of MRTX1719 on MTAP‐deficient glioma cells in vitro and in vivo." (PMID 39711357, 2024). "However, it is regretful that highly elevated MTA levels found in MTAP‐deleted glioma cell lines in culture cannot be extrapolated to primary GBMs." (PMID 39711357, 2024). "Despite the frequent loss of MTAP expression in high-grade gliomas, MTAP did not appear to be associated with a deteriorating outcome, and in-vitro models demonstrated that MTAP did not affect proliferation, invasion, and migration." (PMID 35979371, 2022). "Furthermore, the co-culture of U87 parental MTAP-deleted glioma cells with U87 MTAP-rescued cells resulted in the disappearance of MTA peaks in the 1H-NMR spectrum of the conditioned media." (PMID 34244484, 2021). "Thus, we cultured MTAP-WT macrophages (RAW-264.7) or glioma cells (D423) with labeled methyl tri-deuterated-MTA (D3-MTA)." (PMID 34244484, 2021). "Thus, we sought to match the metabolomic data for different glioma grades with the reported frequency of MTAP deletions in them." (PMID 34244484, 2021).
glioma (continued). "MTAP-intact cases showed intense, uniform staining in both glioma and stromal cells." (PMID 34244484, 2021). "However, no positive correlation was observed between MTAP and AIF in MTAP-intact tumors since both glioma and stromal cells express MTAP in MTAP-intact tumors." (PMID 34244484, 2021). "To verify the diagnosis of homozygous MTAP deletion and contrast this status with the extensive MTAP expression levels in non-malignant tissue, we performed immunohistochemistry on intracranial xenografted gliomas in mice." (PMID 34244484, 2021). "Thus, in homozygous MTAP-deleted tumors, only malignant glioma cells lack MTAP, while stromal cells express normal levels." (PMID 34244484, 2021). "Nevertheless, the clinical and the biological impacts of MTAP are poorly explored in gliomas." (PMID 32093414, 2020). "Moreover, we sought to evaluate, through glioma gene-edited cell lines, the biological impact of MTAP in gliomas." (PMID 32093414, 2020). "This study also showed that, despite the frequent loss of MTAP, it does not have a clinical impact in survival and does not act as a canonic tumor suppressor gene in gliomas." (PMID 32093414, 2020). "Despite the frequent loss of MTAP, it seems not to have a clinical impact in survival and does not act as a canonic tumor suppressor gene in gliomas." (PMID 32093414, 2020). "However, in the context of treatment strategy, MTAP status as a factor of molecular vulnerability to increase the efficacy of treatment in patients with glioma should be further studied with caution." (PMID 32093414, 2020). "In the present study, we evaluated MTAP expression in a large series of gliomas." (PMID 32093414, 2020). "By integrating data from patients and in vitro models, this study showed that, despite the frequent loss of MTAP, it does not have a clinical impact in survival and does not act as a canonic tumor suppressor gene in gliomas." (PMID 32093414, 2020). "It has been shown that the deletion of 9p21, especially co-deletions of CDKN2A/B and MTAP, could be a marker for different grades of glioma." (PMID 31719831, 2019). "Stratifying patients based on MTAP status could open the door for the potential utility of MET-PET as a diagnostic and prognostic tool for gliomas simultaneously addressing the sensitivity of MET-PET." (PMID 29164057, 2017). "The results showed that the inhibitory effect of MRTX1719 on MTAP‐deficient gliomas was significantly attenuated, regardless of whether the proportion of microglia or neurons was at a high or low level." (PMID 39711357, 2024). "Moreover, MTAP’s role in glioma cell proliferation, migration, and invasion was evaluated." (PMID 32093414, 2020). "Moreover, by using glioma cell lines, the biological role of MTAP was evaluated." (PMID 32093414, 2020). "Tissue microarray analysis revealed that the extent of DAB staining for MTAP and PRMT5 was generally higher than that for MAT2A in glioma samples." (PMID 40450009, 2025). "The expression levels of risk factors IL4I1, SMS, and ADI1 in high-grade gliomas were higher than those in lower‐grade gliomas, while the protein expression levels of protective factor GCLC, MSRB2, MTAP and MPST were exactly the opposite." (PMID 38057821, 2023). "This opens new avenues for research in the context of MTAP deficit in cancers including both GBM and lower grade glioma." (PMID 36572880, 2022). "Also based on the glioma subtype analysis, they have shown that all the subtypes showed more than 50% MTAP gene expression loss except for the G-CIMP (Glioma-CpG Island Methylator Phenotype) subtype, and the classical subtype showed the highest frequency of loss of MTAP gene expression." (PMID 36572880, 2022). "Next, we co-cultured MTAP-deleted glioma cells with macrophages (RAW-264.7), immortalized normal human astrocytes, and isogenic MTAP-rescued cells (U87-MTAP) and measured MTA levels in conditioned media using 1H-NMR." (PMID 34244484, 2021).
glioma (continued). "We did not observe statistically significant MTA elevation in GBM tumors with low MTAP expression compared to those with high MTAP expression or GBM tumors with frequent MTAP deletions and grade 2 and 3 glioma tumors with rare MTAP deletions." (PMID 34244484, 2021). "First, we compared MTA levels from the intracellular and extracellular environments of three MTAP-deleted glioma cell lines (U87, Gli56, and SW1088) with MTAP-WT cell lines." (PMID 34244484, 2021). "By performing a systematic analysis of the CNV-driven ceRNAs with clinical features, we found that the CNVs of some genes (such as MTAP/CDKN2A/CDKN2B/KLHL9) had significant impacts on histological diagnosis and survival in glioma." (PMID 31719831, 2019). "We defined the expression below 10% as MTAP deletion, and our analysis showed that MTAP deletion in high‐grade glioma patients is more serious, although it is not twice as high." (PMID 39711357, 2024). "MTAP is frequently co-deleted with CDKN2A in a wide variety of cancers such as malignant pleural mesothelioma, non-small cell lung cancer, and gliomas." (PMID 36572880, 2022). "In silico and in vitro models provided evidences towards the lack of strong biological importance of MTAP in gliomas." (PMID 32093414, 2020). "Our results integrating data from patients as well as in silico and in vitro models provide evidence towards the lack of strong biological importance of MTAP in gliomas." (PMID 32093414, 2020). "Interestingly, CDKN2B, CDKN2A, MTAP, and KLHL9 also belonged to the largest community in the dysregulated ceRNA network, suggesting their possible role to inhibit the development of glioma together." (PMID 31719831, 2019). "Therefore, a homozygous MTAP‐deleted GBM tumor is an admixture of nonmalignant MTAP‐expressing stroma and MTAP‐null malignant glioma cells." (PMID 39711357, 2024). "Moreover, they have shown that MTAP neither has a clinical impact on gliomas nor does it act as a canonic tumor suppressor gene." (PMID 36572880, 2022). "That MTA could still not be detected in these contexts suggests that <1 μM MTA is present in GBM tumors, which supports our conclusion that there are no glioma tumors, regardless of MTAP deletion status, with extreme elevations in MTA." (PMID 34244484, 2021). "However, our data do not rule the possibility of minor accumulation of MTA in MTAP-deleted glioma cells; just that such accumulation would have to be much less than reported in culture." (PMID 34244484, 2021). "Importantly, in U251MTAP−/− and SW1088MTAP+/+ edited glioma cells, we showed that MTAP does not regulate glioma cell proliferation, migration, and invasion mechanisms, major cancer biological features of classic tumor suppressor genes." (PMID 32093414, 2020). "MTAP deficiency may occur without the loss of adjoining CDKN2A in non-small cell lung cancers and gliomas." (PMID 25426549, 2014). "According to a study including 230 glioma cases, among 9p21 deleted cases 10% had CDKN2A HD without MTAP HD." (PMID 38109891, 2024).
pancreatic cancer (28 papers, 2009 to 2026). "In a number of studies associated with breast and pancreatic cancers, MTAP was found to regulate the activity of ornithine decarboxylase (ODC), the rate-limiting enzyme in the biosynthesis of putrescine." (PMID 41439984, 2025). "For instance, the combined use of 2-deoxy-D-glucose (2-DG) and L-alanosine has demonstrated synergistic lethality against MTAP-deficient pancreatic cancer cells." (PMID 40264765, 2025). "The significant association between low MTAP expression and heterozygous MTAP deletions indicates that MTAP expression is gene-dosage-dependent in pancreatic cancer." (PMID 40227771, 2025). "MTAP deletion, prevalent in 20% to 30% of pancreatic cancer cases, is a significant anomaly intricately linked to the disease’s progression." (PMID 39001391, 2024). "Pancreatic cancer organoids were also used to verify that PRMT5 inhibition effectively targets MTAP-deficient tumors." (PMID 37091983, 2023). "MTAP loss has been commonly observed in pancreatic tumors, and is correlated with elevated activity of ornithine decarboxylase (ODC), the rate-limiting enzyme in polyamine synthesis." (PMID 37091983, 2023). "MTAP loss also mediates metabolic adaptation of pancreatic tumor cells to increased glycolytic phenotype and de novo purine synthesis." (PMID 37091983, 2023). "We therefore stably expressed MTAP in MTAP-deficient pancreatic cancer MIA PaCa-2 cells that contain a homozygous deletion of the CDKN2A locus." (PMID 29983885, 2018). "In patients with pancreatic cancer, MTAP deletion often co-occurs with mutations in the KRAS gene." (PMID 41465382, 2025). "Combination treatment strategies have shown promise for MTAP-deficient pancreatic cancer." (PMID 40264765, 2025). "Glycolysis inhibitor 2-deoxy-d-glucose (2-DG) and purine synthesis inhibitor l-alanosine could synergistically exert anti-tumor effect on MTAP-deficient pancreatic cancer cells." (PMID 37091983, 2023). "MTAP loss has been observed in approximately 20% of pancreatic tumors." (PMID 37091983, 2023). "Recent studies on MTAP deletion mutations may provide new ideas for pancreatic cancer treatment." (PMID 40264765, 2025). "The earliest allosteric MAT2A inhibitors with reported efficacy were AG270 and IDE397, which have shown selective inhibition of MTAP-null colorectal cancer, pancreatic cancer, and other solid tumors." (PMID 41439984, 2025). "This pathway involves the MTAP gene, specifically the deletion of the PRMT5 gene (involved in DNA methylation) on chromosome 9p21 found in some pancreatic cancers in MTAP-deficient cells." (PMID 40004658, 2025). "MTAP deletion plays a crucial role in pancreatic cancer research, with approximately 20–30% of pancreatic cancers exhibiting this genetic loss." (PMID 40264765, 2025). "The synergistic effect was also observed in the MTAP‐deleted (CDKN2A‐deleted) pancreatic cancer cell line KP4." (PMID 39309689, 2024). "The currently enigmatic role of MTAP deletion appears to have promising and profound therapeutic implications for metastatic pancreatic cancer." (PMID 39001391, 2024). "The ability of MTAP to suppress pancreatic tumor growth depends on its effect on polyamine production." (PMID 37091983, 2023). "Beyond this general metabolic alteration, MTAP deficiency leads to enhanced expression of hypoxia-inducible factor 1α (HIF1-α) and activation of RIO kinase 1 (RIOK1) in pancreatic cancers, prompting metabolic adaptation towards a glycolytic phenotype and de novo purine synthesis." (PMID 41439984, 2025). "Similarly, ODC inhibition using DFMO in MTAP-null pancreatic tumors led to cell growth inhibition and apoptotic activity." (PMID 41439984, 2025). "The surrogate role of CDKN2A is not clear, and the reported rate of MTAP loss in our cohort was low; the detection method for MTAP loss has not yet validated by comparative genomic hybridization for pancreatic cancer in our NGS testing panel." (PMID 38310130, 2024).
pancreatic cancer (continued). "And the MTAP status of pancreatic tumors is correlated to patient response." (PMID 37091983, 2023). "RIO kinase 1 (RIOK1), a kinase upregulated in MTAP-deleted pancreatic tumor cells, could interact with and phosphorylate HIF1α to affect its stability." (PMID 37091983, 2023). "Interestingly, another report revealed that the p16 gene is often lost along with the MTAP gene in pancreatic cancer." (PMID 30055072, 2018). "In particular, the PRMT5 inhibitor EZP015556 was shown to target pancreatic tumors negative for MTAP (a gene commonly lost in pancreatic cancer), as well as a subset of MTAP-positive tumors." (PMID 40863456, 2025). "The role of MTAP in glycolysis has not been extensively studied, yet one study conducted on pancreatic tumors revealed enrichment of genes involved in the glycolytic pathway in patients with MTAP homozygous deletion." (PMID 41439984, 2025). "Additionally, recent progress has shown new possible approaches to treat pancreatic cancer, such as targeting MDM2 amplification, Claudin 18.2, and MTAP deletion." (PMID 39001391, 2024). "In a pancreatic cancer organoid drug screening study, researchers screened 76 non-clinical compounds and found that PRMT5 inhibitor EZP015556 could be a potential candidate for MTAP-negative pancreatic cancer." (PMID 37576596, 2023). "In addition to isogenic MTAP cell lines, we addressed differential sensitivity between MTAP-proficient and deficient cells towards PRMT5 inhibition in a panel of pancreatic cancer and non-transformed but immortalized cell lines that differ in MTAP status." (PMID 29983885, 2018).